RPS3 (ribosomal protein S3)
Description:
Component of the small ribosomal subunit. The ribosome is a large ribonucleoprotein complex responsible for the synthesis of proteins in the cell. Has endonuclease activity and plays a role in repair of damaged DNA. Cleaves phosphodiester bonds of DNAs containing altered bases with broad specificity and cleaves supercoiled DNA more efficiently than relaxed DNA. Displays high binding affinity for 7,8-dihydro-8-oxoguanine (8-oxoG), a common DNA lesion caused by reactive oxygen species (ROS). Has also been shown to bind with similar affinity to intact and damaged DNA. Stimulates the N-glycosylase activity of the base excision protein OGG1. Enhances the uracil excision activity of UNG1. Also stimulates the cleavage of the phosphodiester backbone by APEX1. When located in the mitochondrion, reduces cellular ROS levels and mitochondrial DNA damage. Has also been shown to negatively regulate DNA repair in cells exposed to hydrogen peroxide. Plays a role in regulating transcription as part of the NF-kappa-B p65-p50 complex where it binds to the RELA/p65 subunit, enhances binding of the complex to DNA and promotes transcription of target genes. Represses its own translation by binding to its cognate mRNA. Involved in spindle formation and chromosome movement during mitosis by regulating microtubule polymerization. Involved in induction of apoptosis through its role in activation of CASP8. Induces neuronal apoptosis by interacting with the E2F1 transcription factor and acting synergistically with it to up-regulate pro-apoptotic proteins BCL2L11/BIM and HRK/Dp5. Interacts with TRADD following exposure to UV radiation and induces apoptosis by caspase-dependent JNK activation.
Synonyms: FLJ26283; FLJ27450; MGC87870; S3; uS3
Tractability: Small molecule: an approved drug acts on it; a structure with a bound ligand is known; a high-quality ligand is known. Antibody: UniProt places it where antibodies can reach, with high confidence; its Gene Ontology location is reachable by antibodies, with high confidence. PROTAC: UniProt records ubiquitination sites on it; ubiquitination databases record sites on it; its protein half-life has been measured; a small molecule that binds it is known. Other modalities: a drug acting on it is in phase 2 or 3 trials.
Target class: Other cytosolic protein
Gene: Protein-coding gene on chromosome 11 (75,394,327 to 75,422,280, forward strand). Ensembl gene ENSG00000149273.
Subcellular location: Cytoplasm; Nucleus; Nucleus, nucleolus; Mitochondrion inner membrane; Cytoplasm, cytoskeleton, spindle
Subcellular location (Human Protein Atlas): Cytosol; Endoplasmic reticulum
Pathways (Reactome):
Metabolism of proteins: Eukaryotic Translation Termination; Formation of a pool of free 40S subunits; Formation of the ternary complex, and subsequently, the 43S complex; GTP hydrolysis and joining of the 60S ribosomal subunit; L13a-mediated translational silencing of Ceruloplasmin expression; PELO:HBS1L and ABCE1 dissociate a ribosome on a non-stop mRNA; Peptide chain elongation; Ribosomal scanning and start codon recognition; SRP-dependent cotranslational protein targeting to membrane; Translation initiation complex formation; ZNF598 and the Ribosome-associated Quality Trigger (RQT) complex dissociate a ribosome stalled on a no-go mRNA
Disease: SARS-CoV-1 modulates host translation machinery; SARS-CoV-2 modulates host translation machinery; Viral mRNA Translation
Metabolism of RNA: Major pathway of rRNA processing in the nucleolus and cytosol; Nonsense Mediated Decay (NMD) enhanced by the Exon Junction Complex (EJC); Nonsense Mediated Decay (NMD) independent of the Exon Junction Complex (EJC)
Cellular responses to stimuli: Response of EIF2AK4 (GCN2) to amino acid deficiency
Developmental Biology: Regulation of expression of SLITs and ROBOs
Metabolism: Selenocysteine synthesis
Gene Ontology:
Molecular function: class I DNA-(apurinic or apyrimidinic site) endonuclease activity; damaged DNA binding; DNA binding; DNA endonuclease activity; DNA N-glycosylase activity; DNA-(apurinic or apyrimidinic site) endonuclease activity; DNA-binding transcription activator activity, RNA polymerase II-specific; DNA-binding transcription factor binding; enzyme binding; Hsp70 protein binding; Hsp90 protein binding; kinase binding; microtubule binding; mRNA binding; oxidized purine DNA binding; oxidized pyrimidine DNA binding; protein binding; protein kinase A binding; protein kinase binding; RNA binding; small ribosomal subunit rRNA binding; structural constituent of ribosome; supercoiled DNA binding; tubulin binding; ubiquitin-like protein conjugating enzyme binding; and 1 more
Biological process: base-excision repair; cellular response to hydrogen peroxide; cellular response to reactive oxygen species; chromosome segregation; DNA damage response; DNA repair; negative regulation of DNA repair; negative regulation of protein ubiquitination; negative regulation of translation; positive regulation of apoptotic signaling pathway; positive regulation of base-excision repair; positive regulation of DNA repair; positive regulation of DNA-templated transcription initiation; positive regulation of gene expression; positive regulation of intrinsic apoptotic signaling pathway in response to DNA damage; positive regulation of microtubule polymerization; positive regulation of non-canonical NF-kappaB signal transduction; regulation of apoptotic process; response to TNF agonist; spindle assembly; cytoplasmic translation; cytoplasmic translational initiation; positive regulation of transcription by RNA polymerase II; translation
Cellular component: cytoplasm; cytosol; cytosolic ribosome; cytosolic small ribosomal subunit; endoplasmic reticulum; extracellular exosome; focal adhesion; membrane; mitochondrial inner membrane; mitochondrial matrix; mitotic spindle; NF-kappaB complex; nucleolus; nucleus; plasma membrane; postsynaptic density; ribonucleoprotein complex; ribosome; ruffle membrane; nucleoplasm; small ribosomal subunit; spindle; synapse
Genetic constraint (gnomAD): Loss-of-function variants: 1 observed, 23.17 expected, observed/expected ratio (o/e) 0.0432, 90% interval 0.014 to 0.2. The upper end of that interval is the gene's LOEUF score, 0.2, which puts it in group 1 of 6, group 1 being the genes least tolerant of losing a copy. Missense variants: 94 observed, 275.41 expected, observed/expected ratio (o/e) 0.34, 90% interval 0.29 to 0.41. Synonymous variants: 105 observed, 102.94 expected, observed/expected ratio (o/e) 1.02, 90% interval 0.87 to 1.2.
Homologues: Orthologues: chimpanzee RPS3 (100% identical), macaque RPS3 (100% identical), pig RPS3 (100% identical), zebrafish rps3 (97% identical), Drosophila melanogaster RpS3 (80% identical), Caenorhabditis elegans rps-3 (74% identical). Paralogues in human: GET1 (16% identical).
Diseases named in the same sentence as RPS3 in open-access papers:
RPS3 is named in the same sentence as 66 diseases in open-access papers, as found by Europe PMC text mining. Sharing a sentence is not in itself a finding about the gene and the disease. The quoted sentences say what the papers report.
colorectal cancer (17 papers, 2016 to 2025). A primary or metastatic malignant neoplasm that affects the colon or rectum. "To this end, we knocked down RPS3, RPS6 and RPS20 as well as RPL7 in human HCT116 colorectal cancer cells that are either WT or deficient for p5343." (PMID 39609413, 2024). "Another study has confirmed that UBE2J1 inhibits the progression of colorectal cancer by enhancing the ubiquitination and degradation of RPS3." (PMID 38656363, 2024). "It has been established that RPS3 expression is relatively higher in colorectal cancer and adenoma, compared to normal colon mucosa." (PMID 36567344, 2023). "circPLCE1-411 promotes the ubiquitin-dependent degradation of the critical NF-κB regulator RPS3 by directly binding the HSP90α/RPS3 complex to inhibit the NF-κB signaling pathway in colorectal carcinoma (CRC)." (PMID 37828589, 2023). "Increased expression of ribosomal protein genes including rpS3, rpS6, rpS8, rpS12 and rpL5 has been reported in colorectal cancer." (PMID 32973493, 2020). "Notably, in colorectal cancer, the RPS3-IκBα interaction modulates IκBα ubiquitination, thereby influencing NFκB pathway activation." (PMID 39425205, 2024). "Thus, SA negatively regulates the function of RPS3 as a potential mechanism for its protective effects against colorectal cancer." (PMID 36672154, 2023). "In colorectal cancer, the elevation of some specific small RPs, including RPS3, RPS6, RPS8, and RPS12, increases ribosome biogenesis and possibly leads to the activation of extra-ribosomal functions such as DNA replication, RNA splicing and modification, and cell growth." (PMID 35159381, 2022). "In addition, rpS3 is overexpressed in colorectal cancer cells, which suggests that there may be a relationship between the occurrence of colorectal cancers and rpS3." (PMID 34745438, 2021). "Furthermore, rpS3 is overexpressed in colorectal cancer cells, suggesting that the level of rpS3 may be related to tumorigenesis." (PMID 27384988, 2016). "In colorectal cancer, UBE2I has been found to inhibit cancer progression by promoting the ubiquitination and degradation of RPS3." (PMID 40025314, 2025). "The silencing of RPS3 reduced cyclin-dependent kinase 4 (CDK4) expression and induced G1 phase arrest in human colorectal cancer cells, which were also observed after treatment with SA." (PMID 36672154, 2023). "For example, the expression of RPL5, RPS3, RPS6, RPS8, and RPS12 in colorectal cancer was higher than that in normal colorectal mucosa." (PMID 33584809, 2020).
viral infection (14 papers, 2008 to 2025). "Our results reveal that during viral infection, an additional copy of rpl40 localizes proximal to rpS3 by the mRNA entry tunnel in the 40S ribosomal subunit, and that these ribosomes can bind directly to viral mRNAs." (PMID 41279401, 2025). "Thus, viral infection remodels ribosomes by directing rpL40 through the N-terminus to a non-canonical site near rpS3 at the mRNA entry tunnel." (PMID 41279401, 2025). "Intriguingly, these uS3 (RPS3) residues are crucial for the inhibition of cellular mRNA translation by the SARS-CoV-2 nonstructural protein NSP1 upon viral infection and their binding to the ribosome; furthermore, R116 is involved in mRNA degradation induced by the viral protein." (PMID 37511213, 2023).
breast carcinoma (6 papers, 2016 to 2025). "RPS3, which is known to interact with NFκB, is overexpressed in breast cancer by up-regulating the X-linked inhibitor of apoptosis (XIAP)." (PMID 34873618, 2021). "Some of the screened proteins, like RPS3, GDI2, IARS2, were less investigated and their cancer-related mechanism and roles remain unclear in breast cancers." (PMID 33194682, 2020). "The expression of ZFAS1 was not significantly different in breast cancer patients as compared to healthy controls (P = 0.4941), which was the case also with RPS3 (P = 0.14)." (PMID 27871336, 2016).
colon cancer (6 papers, 2021 to 2023). "RPS3 is a constituent protein of the 40S small subunit of the ribosome, which has been reported to be a putative marker of malignancy of colon cancer, osteosarcoma, hepatic cell carcinoma, glioblastoma, and mediate Chemotherapy resistance in gastric cancer." (PMID 35847905, 2022). "Analyzing the gene-expression profiles for almost 50 genes of 20 CRC tumors have shown that RPS3, S3A, S4X, S27a, L3, L6, L9, S2 are all overexpressed in colon cancer." (PMID 34873618, 2021). "Studies have also shown that ribosomal protein S3 (RPS3) is highly expressed in colon cancer." (PMID 33854615, 2021). "In colon cancer, the highest correlation was found between CD4+ T cells and RPS14 (correlation = −0.5) and CD4+ T and RPS15A (correlation = −0.49), as well as dendritic cells and RPS3 (correlation = −0.49)." (PMID 35127345, 2022).
gastric cancer (6 papers, 2012 to 2023). A primary or metastatic malignant neoplasm involving the stomach. "All the findings demonstrated that cisplatin-resistant gastric cancer cells communicate with sensitive cells through the delivery key exosomal protein RPS3 and the activation of PI3K-Akt-cofilin-1 signaling pathway." (PMID 33644057, 2021). "In this study, cisplatin-resistant gastric cancer cell line SGC7901R was determined by LC-MS/MS with increased exosomal levels of RPS3 protein." (PMID 33644057, 2021). "All these findings demonstrated that cisplatin-resistant gastric cancer cells communicate with sensitive cells through the intercellular delivery of exosomal RPS3 and activation of the PI3K-Akt-cofilin-1 signaling pathway." (PMID 33644057, 2021). "In this study, a cisplatin resistant gastric cancer cell line SGC7901R was determined by LC-MS/MS with increased exosomal levels of RPS3 protein." (PMID 33644057, 2021). "Further mechanism study demonstrated that cisplatin-resistant gastric cancer cell-derived exosomal RPS3 enhanced the chemoresistance of cisplatin-sensitive gastric cancer cells through the PI3K-Akt-cofilin-1 signaling pathway." (PMID 33644057, 2021). "Ribosomal protein S3 (RPS3) is a highly expressed protein in the exosomes of gastric cancer cells." (PMID 36076942, 2022). "Targeting exosomal RPS3 protein in cisplatin-resistant gastric cancer cells may thus be a promising strategy to overcome cisplatin resistance in gastric cancer." (PMID 33644057, 2021). "A further mechanism study demonstrated that cisplatin-resistant gastric cancer cell-derived exosomal RPS3 could enhance the chemoresistance through the PI3K/Akt-mediated mitochondrial translocation of cofilin-1." (PMID 33644057, 2021). "Exosomal delivery of RPS3 protein may induce chemoresistance phenotypes from cisplatin-resistant gastric cancer cells to sensitive cancer cells by regulating the PI3K-Akt-cofilin-1 signaling pathway." (PMID 33644057, 2021). "Therefore, exosomal RPS3 protein in cisplatin-resistant gastric cancer cells may thus be a promising strategy to overcome cisplatin resistance in gastric cancer." (PMID 33644057, 2021). "For example, RPS3 is involved in the onset of cancer, RPS13 and RPL23 promote the multidrug resistance of gastric cancer cells, and RPL19 is involved in the prognosis of prostate cancer and CRC." (PMID 22272377, 2012).
osteosarcoma (6 papers, 2015 to 2023). A usually aggressive malignant bone-forming mesenchymal neoplasm, predominantly affecting adolescents and young adults. "Studies conducted later revealed that ribosomal protein S3 was responsible for regulating osteosarcoma cell invasion caused by GLI2." (PMID 37176108, 2023). "In response to stress, uS3/RPS3, uS4/RPS9, uS17/RPS11, eS24/RPS24, eL6/RPL6, uL13/RPL13A, eL14/RPL14, eL30/RPL30, eL42L/RPL36AL, and RACK1 in U2OS (human osteosarcoma) cells have O-linked β-N-acetylglucosamine (O-GlcNAc) modifications." (PMID 37047306, 2023). "Overexpression of RPS3 increases the metastasis of osteosarcoma cells." (PMID 29899399, 2018). "The forced expression of RPS3 increased migration and invasion of osteosarcoma cells." (PMID 26336993, 2015). "Thus, RPS3 regulates Hh/Gli2 signalling in the invasion and metastasis of osteosarcoma." (PMID 29899399, 2018). "Since the expression of ribosomal protein S3 was higher in osteosarcomas with lung metastases compared to specimens that were not disseminated, this study suggested this signaling axis as a new marker of invasive osteosarcoma." (PMID 37176108, 2023). "Importantly, immunohistochemical analysis demonstrated that RPS3 levels are much higher in osteosarcoma specimens with lung metastases than in those without metastasis." (PMID 29899399, 2018). "Also, rpS3 regulates GLI2-mediated cancer invasion and metastasis in osteosarcoma." (PMID 27384988, 2016).
glioblastoma (5 papers, 2021 to 2024). The most malignant astrocytic tumor (WHO grade IV). "Additionally, ubiquitination of RPS3 has been linked to enhanced resistance of glioblastoma cells to radiotherapy and decreased apoptosis." (PMID 38528516, 2024). "For example, RNF138 induces ubiquitin-dependent degradation of RPS3 and subsequently leads to radioresistance in glioblastoma (GBM) cells." (PMID 36567344, 2023). "Ribosomal protein S3 is suggested to be a substrate for induction of radio- resistance in glioblastoma." (PMID 33803224, 2021). "Additionally, ubiquitinated degradation of RPS3 is crucial for the emergence of radiation resistance in glioblastoma, underscoring its major role in initiating apoptosis in glioblastoma." (PMID 38528516, 2024). "In highly malignant glioblastomas, the E3 ubiquitin ligase RNF138 has been shown to mediate ribosomal protein S3 (rpS3) ubiquitination, thereby inhibiting rpS3/DDIT3-mediated apoptotic signaling when stimulated by radiation and inducing radioresistance in glioblastoma (GBM) cells." (PMID 38137461, 2023).